DLEU2L (deleted in lymphocytic leukemia 2 like)
Synonyms: formerly BCMSUNL
Gene: Long non-coding RNA gene on chromosome 1 (63,547,082 to 63,550,636, forward strand). Ensembl gene ENSG00000116652.
Diseases named in the same sentence as DLEU2L in open-access papers:
DLEU2L is named in the same sentence as 3 diseases in open-access papers, as found by Europe PMC text mining. Sharing a sentence is not in itself a finding about the gene and the disease. The quoted sentences say what the papers report.
pancreatic cancer (2 papers, 2021 to 2024). "Overexpression of DLEU2L and miR-210-3p interference effectively inhibited pancreatic tumor progression, indicating that DLEU2L plays a crucial role in miR-210-3p-mediated GEM resistance." (PMID 39882259, 2024). "Collectively, these findings indicate that DLEU2L overexpression or miR-210-3p interference effectively disrupted pancreatic tumor growth by suppressing tumor cell proliferation." (PMID 33968986, 2021). "Our report provides the first evidence suggesting that DLEU2L acts as a tumor suppressor by targeting the oncogenic miR-210-3p to attenuate GEM resistance in pancreatic cancer cells." (PMID 33968986, 2021). "Overexpression of DLEU2L and silencing of miR-210-3p suppressed the proliferation, migration, and invasion of pancreatic cancer cells while promoting apoptosis." (PMID 33968986, 2021). "Herein, the overexpression of DLEU2L in pancreatic cancer cells successfully downregulated the expression of GLUT1, LDHB, HK2, and PKM2, which are positive regulators of the Warburg effect." (PMID 33968986, 2021). "Based on this result and our previous findings, we next assumed that DLEU2L plays a tumor-suppressing role, particularly in pancreatic cancer, as a target of (and in turn, by targeting) miR-210-3p." (PMID 33968986, 2021). "DLEU2L (deleted in lymphocytic leukemia 2-like), which is expressed at low levels in pancreatic cancer tissues, was shown to exhibit a binding relationship with miR-210-3p." (PMID 33968986, 2021). "In vivo, DLEU2L overexpression and miR-210-3p interference suppressed pancreatic tumor progression, consistent with the results of in vitro studies." (PMID 33968986, 2021). "Considering the previously analyzed results of apoptosis, these observations signify that DLEU2L overexpression or miR-210-3p interference promoted pancreatic cancer cell death by inhibiting AKT/mTOR activation, and the effects are more prominent at higher GEM concentrations." (PMID 33968986, 2021). "Furthermore, we demonstrated the involvement of AKT/mTOR signaling in DLEU2L-mediated pancreatic tumor suppression." (PMID 33968986, 2021). "Based on the results of bioinformatics analysis, we investigated whether overexpression of DLEU2L or silencing of miR-210-3p affected the biological behavior of PANC-1 pancreatic cancer cells." (PMID 33968986, 2021). "We evaluated whether the overexpression of DLEU2L impairs pancreatic cancer progression in vitro and tumor development in vivo using a nude mouse xenograft model, by examining cancer cell proliferation, apoptosis, glucose metabolism, drug resistance, and molecular signaling pathways." (PMID 33968986, 2021).
tumor (1 paper, 2021). "Herein, we identified DLEU2L (deleted in lymphocytic leukemia 2-like) as a tumor-suppressing lncRNA that exhibits a binding relationship with miR-210, thereby downregulating miR-210 upon interaction." (PMID 33968986, 2021). "We measured the expression of DLEU2L and miR-210-3p in tumor tissues." (PMID 33968986, 2021).
DLEU2L also shares sentences with these, for which no sentence is quoted: pancreatic adenocarcinoma (1 paper).